REN (renin)
Diseases named in the same sentence as REN in open-access papers (continued):
Sharing a sentence is not in itself a finding about the gene and the disease.
secondary hypertension (23 papers, 2014 to 2026). High blood pressure caused by an underlying medical condition. "Page kidney is defined as a rare cause of secondary hypertension due to a subcapsular hematoma externally compressing the kidney resulting in the activation of the renin-angiotensin-aldosterone system (RAAS)." (PMID 38883132, 2024). "The release of renin stimulates a cascade of events that activates angiotensin II, which is responsible for systemic vasoconstriction, and releases aldosterone, which retains sodium and water and causes secondary hypertension." (PMID 39479462, 2024). "We presumed that MSK may be associated with secondary hypertension, and the mechanism may be the activation of the renin-angiotensin-aldosterone system." (PMID 33546058, 2021). "An extensive initial investigation for secondary hypertension (renal Doppler, echocardiography, catecholamine levels, cortisol, and renin-aldosterone system) was normal." (PMID 42137701, 2026). "This pathophysiology underlies the so-called Page kidney phenomenon, in which persistent parenchymal compression activates the renin–angiotensin–aldosterone system and leads to secondary hypertension." (PMID 41462955, 2025). "The current patient was diagnosed with paraneoplastic secondary hypertension due to the presence of disseminated renin-secreting DSRCT." (PMID 25289084, 2014). "Page kidney is defined as a rare cause of secondary hypertension due to the external compression of the kidney by a subcapsular hematoma, of either traumatic or non-traumatic origins, activating the renin-angiotensin-aldosterone system (RAAS)." (PMID 38883132, 2024). "PA is a major contributor to secondary hypertension, which is characterized by autonomous secretion of aldosterone independent of renin and sodium levels." (PMID 39010034, 2024). "Laboratory investigations ruled out secondary hypertension etiologies: autoantibodies including ANA, ANCA, anti-dsDNA returned negative, and endocrine profiles including thyroid function, cortisol, renin-angiotensin-aldosterone system were within normal ranges." (PMID 40547031, 2025).
Alzheimer disease (22 papers, 2015 to 2024). A progressive, neurodegenerative disease characterized by loss of function and death of nerve cells in several areas of the brain leading to loss of cognitive function such as memory and language. "Cox regression analysis of the association between incident Alzheimer’s disease and renin-angiotensin system inhibitors and confounding factors (N = 57,420)." (PMID 36949774, 2023). "Overactivity of the classical renin–angiotensin system (cRAS) within the brain has been implicated in the pathogenesis of Alzheimer’s disease (AD)." (PMID 31982938, 2020). "For example, the brain renin–angiotensin system has been implicated in Alzheimer’s disease neuropathology, and it may serve as a novel potential therapeutic target for Alzheimer’s disease." (PMID 38612681, 2024). "An imbalance in the renin–angiotensin system (RAS) is associated with cognitive decline and disease pathology in Alzheimer’s disease (AD)." (PMID 35396835, 2022). "Enrichment analysis of those networks showed multiple shared pathways associated with disease-related signaling, TGF-beta regulation of extracellular matrix, renin-angiotensin pathway, Alzheimer-disease, and AP-1 transcription factor network." (PMID 33233425, 2020). "Studies have found that mitochondrial dysfunction and also vascular endothelial damage and the dysfunction of the renin-angiotensin system are also involved in Alzheimer’s disease (AD) development." (PMID 32187996, 2020). "Genetic, clinical and epidemiological data as well as experimental cell and animal studies all support a role for the renin-angiotensin system (RAS) in the pathogenesis of Alzheimer’s disease (AD)." (PMID 27884212, 2016). "Chronically overactivated renin–angiotensin system (RAS) signaling is implicated in age-related diseases, including cardiac and renal disease, and neurodegenerative diseases, including Alzheimer’s disease (AD; reviewed)." (PMID 37813091, 2024). "The renin–angiotensin system (RAS) is dysregulated in Alzheimer’s disease (AD)." (PMID 37813091, 2024). "The following LPS-stimulated biological processes were activated by TAK 242: Alzheimer disease, renin secretion, nicotinate and nicotinamide metabolism, C-type lectin receptor signaling pathway, PPAR signaling pathway, and non-alcoholic fatty liver disease (NAFLD)." (PMID 34884814, 2021). "Hyperactivity of the classical axis of the renin-angiotensin system (RAS), mediated by angiotensin II (Ang II) activation of the angiotensin II type 1 receptor (AT1R), is implicated in the pathogenesis of Alzheimer’s disease (AD)." (PMID 27884212, 2016). "Moreover, it was suggested that the ACE-mediated control of the renin-angiotensin system may play a role in the cognitive decline of patients with Alzheimer’s disease." (PMID 37630190, 2023). "The renin-angiotensin system (RAS) is a paracrine RAS within the central nervous system (CNS) and is closely related to Alzheimer’s disease (AD)." (PMID 34827486, 2021). "The Renin–Angiotensin System (RAS) has attracted considerable interest beyond its traditional cardiovascular role due to emerging data indicating its potential involvement in neurodegenerative diseases, including Alzheimer’s dementia (AD)." (PMID 37765259, 2023).
Ascites (22 papers, 2007 to 2025). Accumulation of fluid in the peritoneal cavity (between the layers of the peritoneum that lines the abdomen). "Multivariate analyses revealed that low CP scores (HR, 62.7; 95% confidence interval (CI), 1.5–4526; p = 0.028) and low serum renin concentration (HR, 48.4; 95% CI, 4.6–1483; p < 0.01) were associated with satisfactory control of refractory ascites." (PMID 36143954, 2022). "The course of control of ascites was analyzed in 81 patients whose serum renin and aldosterone concentration were examined before RFX treatment." (PMID 36143954, 2022). "It is also in line with previous studies that showed elevated plasma levels of renin, proBNP and copeptin particularly in cirrhotic patients with ascites or other PH-related complications." (PMID 34021479, 2021). "When ascites is further aggravated, the renin-angiotensin-aldosterone system (RAAS) is significantly activated, resulting in renal sodium and water retention, which is necessary to replenish the intravascular volume in order to maintain hemodynamic stability." (PMID 32676484, 2020). "Our study revealed the effects of RFX against refractory ascites, suggesting that renin concentration may be a predictive marker for assessing ascites control." (PMID 36143954, 2022). "The findings of our study suggested that 41 pg/mL or lower renin concentration before RFX administration could be predictive of the ascites-improving effect of RFX." (PMID 36143954, 2022). "Ascites triggers the activation of neurohumoral systems, the renin-angiotensin-aldosterone system, and the sympathetic nervous system (SNS); subsequently, ascites triggers the non-osmotic activation of antidiuretic hormone, which is a compensatory mechanism of organic homeostasis." (PMID 28792999, 2017). "In addition, albumin administration to cirrhotic patients with ascites has been shown to result in markedly reduced plasma renin activity, aldosterone levels and muscle sympathetic nerve activity in a number of patient types with ascites." (PMID 26606982, 2015). "Secondary endpoints included changes in clinical symptoms, Child–Pugh (CP) score, number of hospitalizations, degree of refractory ascites, adverse events, and the relationship between RFX administration and the renin-angiotensin-aldosterone system." (PMID 36143954, 2022). "By design, creatinine, aldosterone levels, and plasma renin activity were higher in cirrhotic patients with ascites than in patients without ascites." (PMID 26665009, 2015). "Furthermore, both drugs (dapagliflozin or furosemide) hastened the resolution of experimentally induced ascites, but unlike furosemide, dapagliflozin had no significant deleterious effects on hemodynamics, circulating catecholamine concentrations, or the renin-aldosterone axis." (PMID 33457424, 2020).
end-stage renal disease (22 papers, 2012 to 2026). "Monocyte chemoattractant protein 1 (CCL2) is a chief mediator of renin angiotensin system cytokines and emerges in the kidneys of diabetic neuropathy patients, leading to end stage renal failure." (PMID 35154608, 2021). "It is tempting to speculate that in early CKD stages, ACE expression may be still regulated by the renin-angiotensin-aldosterone system, whereas this regulatory loop is abrogated in end-stage renal disease." (PMID 39717170, 2024).
pulmonary hypertension (22 papers, 2016 to 2025). Increased pressure within the pulmonary circulation due to lung or heart disorder. "We evaluated the effects of fenofibrate (FF) in a SU5416/hypoxia model of pulmonary arterial hypertension (PAH) with a specific focus on its influence on the renin–angiotensin system (RAS)." (PMID 41226292, 2025). "Substantial evidence supports the involvement of the renin-angiotensin system in pulmonary hypertension (PH), and the angiotensin II type 2 receptor (AT2R) is known to exert tissue protective actions." (PMID 37108643, 2023). "Idiopathic pulmonary arterial hypertension, pulmonary arterial hypertension, hypertensive nephropathy, and renin-induced hypertension are all examples of EH-like disorders associated with the identified EH genes (Supplementary S4)." (PMID 35629146, 2022). "Pulmonary arterial hypertension (PAH) is commonly accompanied with the activation of the renin-angiotensin-aldosterone system (RAAS)." (PMID 27724864, 2016). "This pattern may reflect inflammation- and hypoxia-driven activation of endothelin-1 and the renin–angiotensin–aldosterone system, leading to significant vasoconstriction, pulmonary hypertension, and eGFR decline with evolving CKD." (PMID 41010963, 2025). "Vitamin D counteracts the vasoconstriction, pulmonary hypertension, coagulation, and interstitial fibrosis caused by SARS-CoV-2 by inhibiting the transcription factor CREB to down-regulate renin, the rate-controlling step of the RAS system, resulting in reduced Ang-II production." (PMID 39452140, 2024). "Recently, consistent data showed that hypoglycemic agents targeting PPARγ as well as renin–angiotensin system inhibitors and mineralocorticoid receptor blockers may influence pulmonary hemodynamics in different models of pulmonary hypertension." (PMID 30791536, 2019). "OLFR78 reduces the conversion of angiotensin I within the renin-angiotensin system by modulating renin secretion, thereby downregulating downstream pathways that elevate blood pressure, contributing to the regulation of pulmonary hypertension and adaptation to high-altitude environments." (PMID 41277956, 2025). "Nocturnal pulmonary hypertension, increased atrial natriuretic peptide release, altered renin–angiotensin–aldosterone activity, and high levels of endothelin may explain the altered fluid distribution in OSA featuring nocturnal polyuria, peripheral edema, and hemoconcentration." (PMID 40968498, 2025). "Theoretically, the course of pulmonary hypertension may be aggravated by the activation of the efferent sympathetic bundles, leading to vasoconstriction, sodium retention, and release of renin from juxtaglomerular cells, and promoting the production of angiotensin II and aldosterone." (PMID 34765677, 2021). "The activation of neurohormones and the renin-angiotensin-aldosterone system (RAAS) leads to systemic and pulmonary artery stiffness, pulmonary hypertension, and right ventricular failure." (PMID 40959696, 2025). "The autonomic nervous system (ANS) and renin-angiotensin-aldosterone system (RAAS) are involved in many cardiovascular disorders, including pulmonary hypertension (PH)." (PMID 33266371, 2020). "Those “other” included miscellaneous cardiovascular agents, vasodilators, vasopressors, agents for pulmonary hypertension, aldosterone receptor antagonists, and renin inhibitors; and they were not considered in this study." (PMID 29682516, 2018).
hypothyroidism (21 papers, 2015 to 2025). Abnormally low levels of thyroid hormone. "Hypothyroidism can manifest as decreased cardiac output and blood pressure, which is associated with a low plasma renin concentration and activity." (PMID 40860776, 2025). "Individuals with hypothyroidism experience significant changes in blood volume, triggering a volume-dependent blood pressure elevation mechanism which is associated with low plasma renin activity." (PMID 40150632, 2025). "This is because hypothyroidism renders the kidneys less sensitive to β-adrenergic stimulation, resulting in reduced renin gene expression and release, and ultimately, reduced RAAS activity." (PMID 40860776, 2025). "Decreased metabolic activity of hypothyroidism leads to a decline in peripheral oxygen demand and reduced renin clearance, leading to expansion of blood volume through sodium reabsorption." (PMID 39967991, 2024). "This review explores the relationship between sodium dysregulation and endocrine disturbances, particularly focusing on primary and secondary hypothyroidism, hypocortisolism, and the renin–angiotensin–aldosterone system (RAAS)." (PMID 39337343, 2024). "It is suggested that hypothyroidism reduces kidney function via decreased cardiac output, increased vascular resistance, and an altered renin–angiotensin–aldosterone system." (PMID 36832157, 2023). "At the same time, renin activities were significantly elevated during the normalization of hypothyroidism, just like in previous studies." (PMID 36187132, 2022). "Animal models of maternal hypothyroidism have also revealed a variety of anomalies, which are involved in cardiac function, including the renin-angiotensin system, beta-adrenergic system, and endothelial functions." (PMID 34531830, 2021). "Hypothyroidism initially decreases peripheral vascular resistance and blood pressure and subsequently activates the renin–angiotensin–aldosterone system, which increases tubular sodium reabsorption." (PMID 28626447, 2017). "Thus, diastolic blood pressure is elevated, pulse pressure is reduced, and renin levels are reduced in hypothyroidism." (PMID 41367395, 2025). "Furthermore, patients with hypothyroidism often have lower plasma renin activity and plasma aldosterone concentrations which can be explained as a humoral response to extracellular fluid retention." (PMID 36187132, 2022). "Although hypothyroidism markedly lowered serum renin, the change was nonsignificant while it was significantly increased (P <0.05) in Fosinopril and Aliskiren groups when compared to the hypothyroid group and normal rats." (PMID 31396276, 2019). "The aldosterone secretion stimulating effects of the increased renin activity and potassium concentrations may be counterbalanced by the simultaneous elevation of ANH levels (measured as NT-proBNP) during the correction of hypothyroidism." (PMID 36187132, 2022). "Eplerenone indicated a significant increase in renin and angiotensin I from 184.09 pg/ml and 178.66 pg/ml to 603.31 pg/ml and 250.88 pg/ml, respectively, meanwhile, aldosterone indicated no significant changes after inducing hypothyroidism and eplerenone administration." (PMID 31579950, 2019).
osteoporosis (21 papers, 2013 to 2025). A condition of reduced bone mass, with decreased cortical thickness and a decrease in the number and size of the trabeculae of cancellous bone (but normal chemical composition), resulting in increased fracture incidence. "MQEP exerts anti-osteoporosis effects and prevents bone loss by alleviating vascular injury caused by renin-angiotensin-aldosterone system activation and promoting type H blood vessel formation." (PMID 36147560, 2022). "The renin-angiotensin system having been associated with bone remodeling in osteoporosis, in addition, Ang II has been identified as an essential pathophysiological activator of inflammatory mechanisms." (PMID 34884653, 2021). "Hyperparathyroidism increases PTH levels and promotes bone absorption, which increases the risk of osteoporosis, indicating that the renin-angiotensin-aldosterone system (RAAS) is associated with osteoporosis." (PMID 32973674, 2020). "This study aims to investigate whether gut microbiota dysbiosis causes osteoporosis through local renin-angiotensin system (RAS)." (PMID 41458549, 2025). "Research has linked bone remodeling in osteoporosis to the renin-angiotensin system." (PMID 37795376, 2023). "Studies have shown that excessive activation of RAS causes osteoporosis, mainly through an elevation of osteoclastic bone resorption, by using a transgenic mouse model overproducing human renin and angiotensinogen or an infusion of AngII in ovariectomized rats." (PMID 23971050, 2013). "Dysbiosis of the gut microbiota leads to osteoporosis by enhancing the activity of the local renin-angiotensin system in bones." (PMID 41458549, 2025). "Abnormal expression of components of renin-angiotensin system and bradykinin receptor-2 in bone tissue also lead to osteoporosis in db/db mice." (PMID 32080264, 2020). "Furthermore, it has been suggested that, especially under hypertensive conditions, vascular calcification and osteoporosis share pathophysiological mechanisms involving the renin-angiotensin system (RAS)." (PMID 36838684, 2023). "Numerous investigations reported that the local expression of RAS components such as renin, ACE-1, and AngII receptors in the skeletal system plays a vital role in local bone remodelling and participates in the progress of osteoporosis." (PMID 38200474, 2024). "In another study which used a chimeric RAS model of transgenic THM (Tsukuba hypertensive mouse) expressing the human renin and human angiotensinogen genes, a recent study showed that the activation of RAS induces high turnover osteoporosis." (PMID 23971050, 2013). "By contrast, people living in a nursing home were less commonly prescribed statins (RR = 0.2), nonsteroidal antiinflammatory drugs (NSAIDs) (RR = 0.3), osteoporosis drugs (RR = 0.3), thiazide diuretics (RR = 0.4), calcium channel blockers (RR = 0.5) or renin–angiotensin inhibitors (RR = 0.5)." (PMID 30782115, 2019). "By contrast, people living in a nursing home were less commonly issued statins (RR = 0.2), nonsteroidal antiinflammatory drugs (NSAIDs) (RR = 0.3), osteoporosis drugs (RR = 0.3), thiazide diuretics (RR = 0.4), calcium channel blockers (RR = 0.5) or renin–angiotensin drugs (RR = 0.5)." (PMID 30782115, 2019).